CBL (Cbl proto-oncogene)
Diseases named in the same sentence as CBL in open-access papers (continued):
Sharing a sentence is not in itself a finding about the gene and the disease.
tumor (continued). "The Casitas B-lineage lymphoma (CBL) family, as a class of ubiquitin ligases comprising c-CBL, CBL-b, and CBL-c, can regulate signal transduction in multiple tyrosine kinase-dependent pathways to mediate tumor growth." (PMID 40165954, 2025). "Then, we detected the function of CBL knockdown on tumor growth and CD8+ T cell infiltration." (PMID 39964752, 2025). "A new role of c-CBL in preventing tumor invasion has been discovered." (PMID 39130630, 2024). "Importantly, only the triple anti-PD-1 + anti-LAG-3 + CBL-Bi combination showed a significant delay in tumor growth." (PMID 39030301, 2024). "Both classifications exclude JMML from the category of overlap neoplasms, since JMML is a pediatric-onset entity with germline predisposition, typically characterized by the presence of germline PTPN11, CBL, and NF1 mutations and by predominantly myeloproliferative features." (PMID 37370785, 2023). "As these kinases are proto-oncoproteins, CBLC may serve a tumor suppressive function similar to its close homologs, CBL and CBLB." (PMID 38045004, 2023). "Interestingly, ZC3H15 is able to decrease the mRNA and protein level of CBL through transcriptional regulation, thereby promoting tumor growth." (PMID 35027542, 2022). "We demonstrated that local delivery of gemcitabine using GEM implants inhibited tumor cell growth by promoting c-CBL-mediated degradation of EGFR and inhibiting the proliferation, angiogenesis, and epithelial–mesenchymal transition of pancreatic/biliary tumors." (PMID 32111094, 2020). "Interestingly, the relatively low expression level of c-CBL would suggest that this molecule functions as a tumor suppressor in HNSCC." (PMID 27244893, 2017). "In tumor tissues, low c-CBL expression was concomitant to high MET and pMET expression." (PMID 27244893, 2017). "High MET, low c-CBL expression was detected in 10 cell lines and 73 tumor tissues." (PMID 27244893, 2017). "It is possible that there could be other mechanisms besides CBL/MET interactions that could lead to the in vivo tumor growth decrease with sh-CBL." (PMID 28835699, 2017). "We investigated whether CBL knockdown affects tumor growth in vivo using A549 sh-CBL and H358 sh-CBL cells in mouse xenograft studies." (PMID 28835699, 2017). "For this study we focused our analysis on adjacent normal (n=18) and primary tumor (n=73) cores contained within a TMA that was subjected to immunohistochemistry (IHC) staining to determine the relationship between c-CBL, MET, and phosphorylated MET (Y1230/34/35 and Y1003)." (PMID 27244893, 2017). "Since CBL and CBL-B are negative regulators of immune cell activation, elimination of their function to boost immune cell activities could be beneficial in tumor immunotherapy." (PMID 27276677, 2016). "Thus, c-CBL seems to have a dichotomous role, acting both as a tumor suppressor or oncogene depending on the cancer type and its dominant pathogenic mechanisms." (PMID 27472394, 2016). "On the other hand, c-CBL appears to act as a tumor suppressor in other malignancies." (PMID 27472394, 2016). "From this point of view, CBL may act mainly as a tumor suppressor in the pathogenesis of human cancers." (PMID 27842510, 2016). "In addition, we found the similar SNV frequency in a set of oncogenes and tumor suppressors, such as CBL and MYC, between primary tumors and metastases." (PMID 24405831, 2014). "We confirmed the presence of numerous tumor-specific L1 insertions in these three cancer types and identify two potentially tumorigenic TE insertions, an Alu insertion in the enhancer region of the tumor suppressor gene CBL and an L1 insertion in the first exon of the BAALC gene." (PMID 27900322, 2016). "Thus, if CBL acts as a tumor suppressor or an oncogene is dependent on the cell and tumor types." (PMID 27842510, 2016).
tumor (continued). "By encouraging the ubiquitination and degradation of HER2, Xia Li worked out a design based on the chimeric ubiquitin ligase of CBL to downregulate HER2, which in turn prevented the proliferation of tumor cells." (PMID 39130630, 2024). "In a murine model of bone tumors, the increased expression of c-CBL also decreases RTK expression, leading to reduced proliferation and survival of tumor cells and slowing tumor growth." (PMID 39062505, 2024). "In retrospective analyses, selected cancer-associated mutations and alterations that are putative targets of sitravatinib in vitro (e.g., RET, MET, CBL, AXL, KDR, and NTRK) were monitored from circulating tumor DNA in baseline plasma samples (n = 49)." (PMID 36842467, 2023). "Responses were observed in patients with RCC and NSCLC, and included patients with tumor RET rearrangements, and MET, CBL and AXL alterations." (PMID 35767205, 2022). "CBL possesses a critical role in the regulation of CD8 (+) T cells and CAR T-cell functions to increase immunity against the tumor." (PMID 35027542, 2022). "c-CBL protein expression is low in normal and HNSCC patient tumor specimens, while MET and pMET expression are increased." (PMID 27244893, 2017). "Importantly, the synthetic peptide PVILLISFLI disrupted the PrP/c-CBL/IGF-1R combination in vitro and in vivo, thus reducing cancer cell autophagy and tumor aggressiveness." (PMID 39130630, 2024). "The constitutive tyrosine phosphorylation of c-CBL protein was observed in human tumor cells, but not detected in control ECV304 cells." (PMID 39130630, 2024). "The two most frequently detected variants - CBL p.Asp460del and RUNX1 p.Glu422Ala - were described in various neoplasms, including hematologic, with no confirmed pathogenicity." (PMID 37671053, 2023). "We firstly detected the low expression of CBL in GC cell lines (BGC‐823, MKN‐28, MKN‐45, AGS and SGC‐7901) compared with GES‐1 in mRNA and protein expression levels, implying the potential role in tumour inhibition." (PMID 36000536, 2022). "These suggestive findings make it vital to design models where tissue-specific and tumor-intrinsic deletion of CBL and/or CBL-B can be induced to assess non-myeloid cell and tumor cell-intrinsic roles of CBL proteins." (PMID 27276677, 2016). "Wild type c-CBL is reported as a tumor suppressor in several cancers and acts as a negative regulator of receptor and non-receptor protein tyrosine kinases via their degradation by polyubiquitination." (PMID 27472394, 2016). "Further, for the first time, the new model will allow the role of CBL and CBL-B to be determined in tumorigenesis without the current lack of feasibility of such studies due to tumor rejection from germline deletion of CBL-B using existing models." (PMID 27276677, 2016). "The genetic changes in CBL that belongs to a family of RF (ring finger) ubiquitin ligases in solid tumours is known, while investigation of the same gene in OSCC samples has led to the conclusion that CBL genetic alteration are infrequent in this type of neoplasia." (PMID 40457841, 2025). "Our analysis revealed that P848L (a) does not bind erlotinib; (b) is turned over less rapidly than L858R (a common tumor‐derived EGFR mutation); (c) is not autophosphorylated at Tyr 1045 [the major docking site for Cbl proto‐oncogene (c‐Cbl) binding]; and (d) does not bind c‐Cbl." (PMID 31314158, 2019). "Importantly, this model will allow concurrent CBL and CBL-B deletion in non-hematopoietic tissues to understand the role of these proteins in physiology and tumorigenesis, without spontaneous tumor rejection." (PMID 27276677, 2016). "The establishment of a new model of concurrent tissue-selective CBL/CBL-B deletion should allow a clear assessment of the tumor-intrinsic roles of CBL/CBL-B in non-myeloid malignancies and help test the potential for CBL/CBL-B inactivation in immunotherapy of tumors." (PMID 27276677, 2016).
tumor (continued). "Particularly in the context of tumorigenesis, the available CBL-B-null model has not been suitable for in vivo studies to assess the tumor cell-intrinsic roles of CBL proteins since CBL-B-null mice reject tumors due to their activated CD8+ T-cells and NK cells." (PMID 27276677, 2016).
cancer (104 papers, 2008 to 2026). A tumor composed of atypical neoplastic, often pleomorphic cells that invade other tissues. "The discovery of six amplified (i.e., WHSC1L1, CCND1, and SOX2) and 29 deleted (i.e., NCOR1, SETD2, and CBL) cancer associated genes was highlighted." (PMID 38539567, 2024). "UBASH3B expression is implicated in various cancers through its ability to bind CBL and block its ubiquitination activity." (PMID 38461240, 2024). "The phosphorylation of Y845 has emerged as a significant event in cancer cells, while the phosphorylation of Y1045 is known to be associated with the ubiquitination and degradation facilitated by CBL." (PMID 39130630, 2024). "Another study identified that inhibiting CBL mutations can activate the innate immune system to restrain cancer metastasis and improve the sensitivity to immunotherapy." (PMID 37649078, 2023). "Growing evidence have defined the clinical spectrum of germline CBL mutations configuring the so-called CBL syndrome, a cancer-predisposing condition that has been shown to also include multisystemic diseases." (PMID 35159106, 2022). "Growing evidence have defined the clinical spectrum of germline CBL mutations configuring the so-called CBL syndrome; a cancer-predisposing condition that also includes multisystemic involvement characterized by variable phenotypic expression and expressivity." (PMID 35159106, 2022). "Among those interactors, CBL as a proto-oncogene plays an important role in cancer, whose mutations can enhance the PI3K/AKT signaling." (PMID 36304985, 2022). "Patients with molecularly confirmed CBL germline mutations should receive cancer surveillance and a full screening to assess cardiac, vascular and hematological alterations." (PMID 35159106, 2022). "Our findings provide a rationale for targeting CBL in cancers with CBL mutation or inactivation for therapeutic intervention." (PMID 33627783, 2021). "Secondary outcome measurement is enrichment of RAS regulatory gene (NF1, PTPN11, and CBL) in BRAF variant cancers." (PMID 33507258, 2021). "The oncogenic nature of RTKs, addiction of cancers to growth signals and given the clustering of c-CBL, EGFR and MET mutations, it is possible that the transforming effect of c-CBL mutations is most likely a combinatorial effect of the three." (PMID 20126411, 2010). "Furthermore, disrupting the interaction of CBL mutations with EGFR or CIN85 can also reduce the development of cancer." (PMID 39130630, 2024). "Somatic CBL mutations can be found in different type of cancer." (PMID 35159106, 2022). "From the lncRNA and mRNA associations obtained by cancer co expression analysis, we validated by qRT-PCR, the differential expression of lncRNA T216482 (2 fold down-regulated) and its associated mRNA, CBL (1.9 fold down-regulated) in C + T treated cells compared to control." (PMID 31324852, 2019). "In addition, the important role of cbl family proteins in immunotherapy has been widely demonstrated, and the anticancer effects of CBL proteins can be targeted by specifically modifying their ability to bind to various cancer-causing proteins, making them attractive targets for cancer therapy." (PMID 39130630, 2024). "Our analysis identified cancer as one of the top diseases associated with the significantly differentially expressed lncRNAs and mRNAs and revealed the integrated link between the gene/lncRNA pairs: CBL/T216482 and GDF7 (BMP12)/T185733, prominently associated in cancer pathways." (PMID 31324852, 2019). "This dual role of c-CBL highlights its complex involvement in cancer and suggests that its impact on tumorigenesis can vary depending on the cellular context and specific signaling cascades." (PMID 39130630, 2024). "Numerous studies have demonstrated the important role of CBL in various cellular pathways, particularly those involved in the occurrence and progression of cancer, hematopoietic development, and regulation of T cell receptors." (PMID 39130630, 2024).
cancer (continued). "Our research underscores the significant role of Cbl proto-oncogene (C-CBL) as a neddylation E3 ligase for IRS1 and IRS2, highlighting the promising potential of C-CBL as a target for regulating cancer metastasis in the context of insulin dysregulation." (PMID 38272982, 2024). "The dysregulation of micrornas (mirnas) can lead to cancer, and early studies have found out that CBL is a direct target of miR-200a-3p." (PMID 39130630, 2024). "Some unexplored aspects of CBL biology, such as biomarkers of its activity and its role in other cancer-generating models, still need further study." (PMID 39130630, 2024). "CBL is involved in a variety of cancer-related processes, including angiogenesis and tumorigenesis, holding the major role of proto-oncogene." (PMID 37624039, 2023). "In conclusion, we illustrated the role of ZC3H15 as a transcription factor that stabilized the EGFR protein level via inhibiting CBL transcription to promote cancer progression." (PMID 35027542, 2022). "CBL plays a key role in different cell pathways, mainly related to cancer onset and progression, hematopoietic development and T cell receptor regulation." (PMID 35159106, 2022). "CBL has been reported to play a role in different well-known cell pathways, many of which are related to hematopoietic development, immunology and cancer onset and progression." (PMID 35159106, 2022). "Particularly, CBL has been reported to play a role in different well-known cell pathways, many of those are related to cancer onset and progression, hematopoietic development and T cell receptor regulation." (PMID 35159106, 2022). "To learn more about the underlying mechanism, we tried to predict the potential interactors of SERPINA5, focusing initially on CBL, an E3 ubiquitin ligase of several tyrosine kinase receptors that functions as a suppressor gene in many cancers." (PMID 36000536, 2022). "Circ-ITCH and similar circRNAs promote cancer cells, evading antigrowth signals by enhancing other oncogenes, such as CBL." (PMID 36230649, 2022). "CBL is the gatekeeper to prevent the development of cancer and negatively regulate the PI3K/AKT pathway by binding to the P85 subunit of PI3K to promote its ubiquitination." (PMID 36000536, 2022). "Driver mutations, including RET, CBL, and DDR2 gene mutations, were identified in the hypermutated cancers." (PMID 34503126, 2021). "Together, these results provide a rationale for exploring the potential of targeting the EGFR–CBL–CIN85 axis in CBL-inactivated mutant cancers." (PMID 33627783, 2021). "Cancer driver genes namely CBL, GFI1, RASGRF2 and ELK3 were significantly down-regulated and associated with the significantly down-regulated lncRNAs -T216482, -T334719, -T217484 and -T265137 respectively." (PMID 31324852, 2019). "The role of c-CBL in proliferative cell signaling and cancer has been suggested by a limited number of studies." (PMID 27472394, 2016). "CBL which is involved in cancer initiation and progression and is believed to form a multi-protein complex with BCR-ABL is a putative targets of miRs-31 and miR-155." (PMID 22511990, 2012). "Three of the five tumors had a T2/OncZ insertion in one gene (CBL, TSHR, or SMARCB1) known to be highly mutated in human cancers." (PMID 21533036, 2011). "In a pioneering study, TKamei investigated the expression and tyrosine phosphorylation of the proto-oncogene product c-CBL in different human cancer cell lines and surgical specimens, with the aim to identify the signaling pathways linked to the development of human tumors." (PMID 39130630, 2024). "Interestingly, the CBL mutant is thought to disrupt the original E3 ubiquitin ligase activity and promote cancer onset and progression." (PMID 38643442, 2024).
cancer (continued). "NCOA1 and CBL have previously been shown to play oncogenic roles in many cancers." (PMID 37373553, 2023). "CBL exists in a variety of cancers and is mostly considered to be a tumour suppressor gene." (PMID 36000536, 2022). "RET, CBL, and DDR2 driver mutations might represent potential response markers in hypermutated cancers." (PMID 34503126, 2021). "Studies reveal potential clinical impact of CBL gene on cancer immunotherapy." (PMID 34764329, 2021). "The levels of CIN85 and CBL progressively increase as cancer stages advance." (PMID 33627783, 2021). "In addition, we identified RET, CBL, and DDR2 driver mutations as potential response markers in hypermutated cancers." (PMID 34503126, 2021). "It is noteworthy that abnormal CBL expression is associated with the progression of different types of human cancer, but the status of CBL activation has not been analyzed in these studies." (PMID 33627783, 2021). "Indeed, knocking down CBL in different cancer cells reduces their proliferation, clonogenic survival, and migration." (PMID 33627783, 2021). "Of the remaining 17 variants, all but three are accounted for by six genes (BRAF, CBL, MAP2K1, MAP2K2, RAF1, and SOS1) encoding members of the RAS-MAPK pathway, among which nine variants have previously been reported in either congenital disorders or cancer." (PMID 30355600, 2018). "Importantly, target genes involved in epithelium development (RGMA, SHANK3, PAX6, PFN1, WNT4) and cancer (CBL, CYCS, FGF7, IGF1R, PTEN, PIK3CD, WNT4) address to a further role in the onset of epithelial abnormalities and oncogenesis." (PMID 23936163, 2013). "c-CBL is an E3 ubiquitin ligase and adaptor molecule important in normal homeostasis and cancer." (PMID 20126411, 2010). "Therefore, the CBL and MAPK3 changes observed in this study may reflect a rebalancing of EGFR signaling that can lead to inhibition of cancer cell growth, even in the presence of KRAS mutations." (PMID 41226554, 2025). "Shivanna and colleagues have shown that c-CBL ubiquitin ligase regulates nuclear β-catenin and angiogenesis by affecting its tyrosine phosphorylation via modulations in Wnt signaling, suggesting potential therapeutic benefit of targeting c-CBL in angiogenesis-associated diseases, including cancer." (PMID 27472394, 2016). "Alterations in CBL and MAPK3 reflect a balance of signaling pathways involved in cancer cell growth and survival, particularly the EGFR/MAPK pathway, which plays a key role in stimulating cell proliferation, evading apoptosis, and metastasis." (PMID 41226554, 2025). "All these variants are present in heterozygosity, and many of them occurred in tumor suppressor genes and transcription factors that have a role in cancer development and T cell function, like MSH6, ARID1A, CARD11, CBL and SRC30–33." (PMID 38688902, 2024). "By acting as a regulatory “pin” molecule, CBL can exert control over the activity and expression of SRC, thereby influencing the downstream signaling pathways involved in cancer progression, including the PI3K/AKT pathway." (PMID 39130630, 2024). "Therefore, CBL may also exert a dual function in cancer, depending on the cellular context." (PMID 33670716, 2021). "One was the DEGs between a cancer cell line and the corresponding gene DKO (E3 ubiquitin‐protein ligase (CBL)‐PTPN12 DKO case)." (PMID 34723439, 2021). "For instance, in the current sample, the genes GNAS, GNAQ, and GNA11 were widely altered across cancer types, and these alterations often were accompanied by specific genomic abnormalities in AURKA, CBL, and LYN." (PMID 34150649, 2021). "It has been reported that miR-124 inhibits proliferation in cancer cells through targeting CDK4, CBL, Slug and androgen receptor." (PMID 31367191, 2019).